HIF1A (hypoxia inducible factor 1 subunit alpha)
Diseases named in the same sentence as HIF1A in open-access papers (continued):
Sharing a sentence is not in itself a finding about the gene and the disease.
astrocytoma (28 papers, 2004 to 2025). "In contrast, stepwise upregulation of HIF1A observed in our cases of diffusely infiltrative astrocytomas associated with high expression of LOX and BMP1 suggest progressive activation of both angiogenic and invasive pathways." (PMID 25790191, 2015). "In malignant astrocytomas, HIF-1α was mainly present in cells arranged in a pseudo-fenestrated pattern near the necrotic zone and in cells infiltrating normal tissue around the tumor." (PMID 38734702, 2024). "We further analyzed GSE4290, of which the dataset showed that the levels of HIF-1α were higher in the GBM group than in the astrocytoma groups (grade II and III)." (PMID 32045997, 2020). "In our research, we first found that ANKDD1A plays an important role in regulating the stability of HIF1α in astrocytoma cells under hypoxic conditions." (PMID 30082910, 2019). "In Section 2.1.2, the growth and differentiation of HIF-1α-deficient and VEGF-deficient astrocytomas is also dependent on the inoculation site and its corresponding microenvironment; however, the degree of hypoxia was not quantified in the cited study." (PMID 30420794, 2018). "Intracranial inoculation on the other hand led to accelerated growth of HIF-1α-deficient tumor growth, whereas VEGF-deficient astrocytomas still exhibited a growth disadvantage." (PMID 30420794, 2018). "Based on this, we examined human astrocytoma tissues for HIF-1α-regulated quiescent stem-like tumor cells as a candidate for long-term tumorigenic cells and characterized their niche histologically." (PMID 26799577, 2016). "We attempted to identify HIF-1α-regulated quiescent stem-like tumor cells in astrocytoma tissues using the following immunophenotypes as indices: SOX2+ HIF-1α+ RNApII-S2P-/low or NANOG+ HIF-1α+ RNApII-S2P-/low." (PMID 26799577, 2016). "The results demonstrate that increased expression and activity of LOX, BMP1 and HIF1A were positively correlated with the malignant grade of astrocytomas." (PMID 25790191, 2015). "In the present study, we investigated the expression of LOX, BMP1 and HIF1A in astrocytomas of different malignant grades." (PMID 25790191, 2015). "HIF1A expression levels increased with the malignant grade of astrocytomas, with statistically significant values for all malignant grades of astrocytomas when compared to control samples." (PMID 25790191, 2015). "Many of the genes have in fact been implicated in development of astrocytoma, including EGFR, HIF-1α, c-Myc, WNT5A, and IDH3A." (PMID 23737970, 2013). "In both astrocytomas and hemangioblastomas there was intense staining for both Ndrg1 and HIF-1α in a number of different patients." (PMID 15341671, 2004). "Higher HIF-1α expression in human astrocytoma and GBM has been correlated with worse prognosis." (PMID 33842321, 2021). "Multi-color immunohistochemistry was used to visualize HIF-1α-expressing (HIF-1α+) quiescent stem-like tumor cells and their niche in astrocytoma (WHO grade II–IV) tissues." (PMID 26799577, 2016). "Several of these genes, including MYC, EGFR, HIF1A, HGF, APOE, TIMP3, and WNT5A have been identified as being important to development of astrocytoma." (PMID 23737970, 2013). "However, in the other group, TCGA astrocytoma, A2AR was negatively related to HIF1a, ENPP1 (ectonucleotide pyrophosphatase/phosphodiesterase 1), and pannexin, and positively correlated with ADK (adenosine kinase)." (PMID 37047660, 2023). "In human astrocytoma U251 cells, hepatoma Hep3B cells and an HUVEC culture experimental model, the oligomer procyanidin, which is isolated from grape seeds, can inhibit angiogenesis by suppressing the HIF-1α-dependent pathway." (PMID 34976156, 2022). "BMP1 and HIF1A were positively correlated with the malignant grade of astrocytomas, but no research reported their direct or indirect relationship." (PMID 31155610, 2020). "LOX, BMP1 and HIF1A expression analysis by qRT-PCR showed great variability in astrocytomas of all malignant grades when compared to non-neoplastic samples." (PMID 25790191, 2015).
astrocytoma (continued). "The purpose of our study was to characterize LOX, BMP1 and HIF1A expression by real-time PCR in astrocytomas with WHO grades I to IV compared to non-neoplastic brain tissue." (PMID 25790191, 2015). "To do this, we identified a group of astrocytomas, IDH-mut, grade 3 and grade 4, and oligodendroglioma, IDH-mut, grade 3 (n = 88), with a high level of the HIF-1α hypoxic marker and a group of the same tumor types (n = 80) with a low expression of HIF-1α marker." (PMID 36612140, 2022).
glaucoma (28 papers, 2012 to 2025). Increased pressure in the eyeball due to obstruction of the outflow of aqueous humor. "As a result of hypoxic insults, the hypoxia-inducible factor 1α (HIF-1α), a potent cytokine, triggers downstream transductions that activate glial cells, leading to neuroinflammation, similar to the events observed in glaucoma associated with a high IOP." (PMID 37765001, 2023). "We tested whether chronic HIF-1α signaling alone results in metabolic dysregulation, potentially providing insight into the metabolic deficiencies observed in situations with chronic HIF-1α activation, including glaucoma." (PMID 37996657, 2023). "The presence of increased HIF-1α expression regions in the retina and optic nerve of glaucoma patients was confirmed by Tezel and Wax, further supporting the pathogenic role of hypoxia in glaucoma." (PMID 37508003, 2023). "In glaucoma mice, decreased HIF1α expression is observed to be correlated with RGC loss." (PMID 32867129, 2020). "HIF-1α is closely associated with oxygen-dependent retinal diseases, including von Hippel-Lindau, proliferative diabetic retinopathy, retinopathy of prematurity and glaucoma." (PMID 25891515, 2015). "The glaucoma-related overexpression of HIF-1α observed in MCE-injected animals fed a normal diet was completely suppressed by ACE oil-enriched diet." (PMID 38337691, 2024). "This investigation suggests that mild OSA modestly elevates HIF-1α, oxidative stress, and inflammation, yet it remains to be determined if these changes contribute in meaningful ways to ocular conditions such as glaucoma." (PMID 39061946, 2024). "Our findings suggest that CIH induces oxidative stress, inflammation, and upregulation of HIF-1α in the retina, akin to early-stage glaucoma." (PMID 39061946, 2024). "HIF-1α accumulates under conditions of hypoxia or pseudohypoxia, including in glaucoma, initiating a wide range of physiological responses, including erythropoiesis, glycolysis, and angiogenesis." (PMID 39061946, 2024). "In another study where we assessed the impact of HIF-1α stabilization on mitochondrial homeostasis and oxidative stress in a chronic model of glaucoma, we observed that the expression of LDH-A was unchanged regardless of HIF-1α stabilization." (PMID 39061946, 2024). "Elevated levels of HIF-1α protein have been reported in the retina and ON from glaucoma patients and animal models." (PMID 39061946, 2024). "Previous studies by our group demonstrated high levels of HIF-1α in acute and chronic mouse models of glaucoma." (PMID 37996657, 2023). "Hypoxia-inducible factor 1-alpha (HIF-1α) is upregulated in response to hypoxia in glaucoma patients and can further enhance NOX-2 and inducible nitric oxide synthase (iNOS) expression, resulting in ROS production." (PMID 37765001, 2023). "The glial hypertrophy and activated AMPK after 4 weeks of Roxadustat treatment resemble the conditions observed in chronic HIF-1α activation in glaucoma." (PMID 37996657, 2023). "HIF-1α protein has been reported in the retina and ON from glaucoma patients and animal models, indicating that increased IOP and potentially other mechanisms such as inflammation shift retinal metabolism towards glycolysis, including in the RGCs." (PMID 37996657, 2023). "Despite the evidence of pseudohypoxia in glaucomatous retinas and optic nerves, there are unanswered questions about the size of the role of increased HIF-1α to glaucoma pathogenesis." (PMID 37996657, 2023). "Immunohistochemical analysis of retinas from humans and preclinical animal models of glaucoma have revealed increased levels of HIF-1α relative to healthy controls." (PMID 37996657, 2023). "This interpretation is consistent with other threshold effects that have been seen in induced glaucoma models as well as the differential effects of acute (HIF-1α related) and chronic (HIF-2α related) hypoxia on cellular injury." (PMID 36545655, 2022).
glaucoma (continued). "The hypoxic and oxidative stress environment found in glaucoma is thought to play a significant part in the disease pathogenesis through HIF1α and the induction of aberrant epigenetic modification." (PMID 24800062, 2014). "Regions of HIF1α expression indicate areas of decreased oxygen and so hypoxic stress, which suggests that there is tissue hypoxia in glaucoma and that this plays a role in the disease." (PMID 24800062, 2014). "HIF-1α immunoreacitivity is observed not only in the optic nerve but also in the retina in glaucoma." (PMID 23316132, 2012). "Interestingly, HIF-1α was also found to be upregulated in an inherited glaucoma model of DBA/2J mice and, along with its target gene VEGF, was suggested to participate to in the breakdown of the blood–retinal barrier, thus promoting the loss of RGCs." (PMID 39458974, 2024). "Additionally, the hypoxic immunohistochemical marker HIF-1α in the retina and optic nerve has been noted in glaucoma models and patients." (PMID 38984144, 2024). "Interestingly, HIF-1α was found to be upregulated in tissues from glaucoma patients and in experimental animal models of glaucoma, such as in mice and rats." (PMID 39458974, 2024). "Another interesting link between OSA and glaucoma is hypoxia with upregulation of HIF-1α." (PMID 36077478, 2022). "A recent study demonstrated that glaucoma progression could be accelerated by the interaction between hypoxia-inducible factor (HIF)-1α and vascular endothelial growth factor." (PMID 35692841, 2022). "Hif1a, a master regulator of glycolysis and cell stress responses, was upregulated consistent with stress or inflammation, and with previous findings in the inner retina during glaucoma." (PMID 32450896, 2020). "All these data indicate that HIF-1α expression might be a very crucial stage in glaucoma development and therefore a successful target for the implementation of neuroprotective drugs." (PMID 32710140, 2020). "Moreover, previous histopathological studies in human retinal tissue revealed that expression of the O2 sensing molecule, HIF-1α, is increased in glaucoma and is concordant with the location of visual field defects." (PMID 31976030, 2019). "While the experiments in this manuscript do not test the hypothesis that hypoxia or ischemia is the cause of RGC death and dysfunction, it is intriguing that there is also evidence for HIF-1α upregulation in the RGCs of glaucoma patients." (PMID 29434244, 2018). "This hypothesis is supported by studies showing an increase in levels of HIF1α in the vitreous of glaucoma patients and in animal models." (PMID 26876380, 2016). "In addition to neuron degeneration and vascular damage, the high oxidative stress can contribute to the occurrence of glaucoma, including OAG, and the elevated level of reactive oxygen species can lead to the upregulation of HIF-1a, death of retinal ganglion cells, and subsequent glaucoma." (PMID 39199599, 2024). "A hypoxic element evident by increased hypoxia-inducible factor-1 alpha (HIF1α) in the retina and optic nerve head of human donor eyes with glaucoma and ocular hypertensive mouse eyes may also provide a HIF1α-regulated mechanistic background for increased glycolysis." (PMID 34199494, 2021). "Moreover, in glaucoma donor eyes, an increased expression of HIF-1α could be identified in RGCs and the optic nerve axons." (PMID 32710140, 2020). "Our present results confirmed elevated expression of HIF1-α and VEGF-A in glaucoma, and our findings suggest that PACAP is able to reduce the hypoxia-induced retinal and microvascular damage by decreasing HIF1-α and VEGF-A expression in glaucoma." (PMID 37686074, 2023). "Although HIF-1α increase occurs well before VEGF upregulation, the fact that both markers vary in concert during the progression of glaucoma can be due to the time scale of the present analysis, which overcomes the temporal sequence of VEGF accumulation." (PMID 37174673, 2023).
glaucoma (continued). "In summary, these data provide evidence that chronic HIF-1α and HIF-2α activation, a feature of glaucoma and several retinal diseases, can induce metabolic dysfunction and neurodegeneration." (PMID 37996657, 2023). "It is possible that HIF-1α is not only helpful in classifying and monitoring OSA but can also apply as a possible therapeutic approach to treat glaucoma." (PMID 36077478, 2022). "Several lines of evidence have suggested that HIF-1α overexpression can contribute to retinal pathologies, including retinopathy of prematurity, DR, AMD, glaucoma, and high altitude retinopathy." (PMID 28289375, 2017). "The expression of HIF-1α during RGC degeneration is more evident in human glaucomatous donor eyes, supporting the occurrence of sustained tissue hypoxia in glaucoma." (PMID 23316132, 2012). "An additional sign of glaucoma progression is the accumulation of both HIF-1α and VEGF, to which IOP and non-IOP related mechanisms are likely to contribute." (PMID 37174673, 2023). "Interestingly, in retinas of a high-pressure experimental rat glaucoma model, an upregulation of HIF-1α and some HIF-1α target genes was detectable." (PMID 32710140, 2020). "In accordance, hypoxia, as assayed by pimonidazole immunolabel, was largely absent in the ON and ONH with comparably low labeling in control and the bead glaucoma model after 2 weeks and 4 weeks of IOP elevation; however, there was a significant increase in Hif-1α transcript after 4 weeks of OHT." (PMID 30601926, 2019). "In support of this concept, many previous studies reported on reduced calibre of retinal arterioles, reduced optic nerve head and peripapillary blood flow dynamics, and increased levels of retinal hypoxia markers, such as HIF-1α and VEGF, in eyes of glaucoma patients." (PMID 31976030, 2019). "The efficacy of HIF-1α and its target genes in protecting against RGC degeneration may open new perspectives for the treatment of glaucoma, optic neuritis, and traumatic optic neuropathy injuries." (PMID 28289375, 2017). "We verified whether HIF-1α and VEGF levels were related to glaucoma progression over time." (PMID 37174673, 2023). "Similarly, in the present study, the striking MCE-induced upregulation of HIF-1α was completely suppressed by an ACE oil-enriched diet, suggesting that ACE oil might exert protective functions against retinal ischemic damage characterizing glaucoma." (PMID 38337691, 2024).
myopia (28 papers, 2019 to 2025). "Gene analyses have further described this relationship, revealing a moderate association between the HIF-1α signaling pathway and myopia." (PMID 40933557, 2025). "Studies in mouse models and human cell cultures have shown that the scleral hypoxia-associated HIF-1α pathway plays a pivotal role in myopia development." (PMID 41438149, 2025). "Wu discovered that signaling of HIF-1α promotes myopia by causing fibroblasts to transform into myofibroblasts, and that treatment targeting hypoxia prevented the molecular changes associated with HIF-1α, thus stopping the progression of myopia." (PMID 39624669, 2024). "The scleral hypoxia causes the accumulation of HIF-1α, myofibroblast transdifferentiation, and decreased collagen production, ultimately leading to scleral remodeling and the development of myopia." (PMID 37849748, 2023). "The significant decrease in HIF-1α levels in both low myopia (LM) and HM groups (p < 0.01) may be linked to advanced hypoxic conditions in the sclera, where prolonged tissue stress could influence HIF-1α stabilization or transcriptional activity." (PMID 41438149, 2025). "The inverse association between HIF-1α and both axial length (p < 0.01) and maculopathy severity (p < 0.05), along with its positive correlation with choroidal thickness (p < 0.01), may be associated with a dysregulated hypoxic response in advanced myopia." (PMID 41438149, 2025). "In addition, gene set enrichment analysis (GSEA) of new genome-wide association study (GWAS) data of 593 patients with high myopia (diopter ≤ −6 diopter [D]) found that the HIF-1α signaling pathway was significantly enriched in patients with high myopia (diopter ≤ −10D)." (PMID 39796188, 2025). "The concomitant reduction in VEGF (p < 0.01), a downstream effector of HIF-1α, supports the interpretation of an altered hypoxia–angiogenesis axis in high myopia." (PMID 41438149, 2025). "Along with the down-regulation of NAT2, there was an increase in the expression of hypoxia inducible factor-1α (HIF-1α) in myopic sclera, which was reported as a crucial transcription factor in hypoxic response and involved in myopia pathogenesis." (PMID 41169617, 2025). "This suggests that HIF-1α signaling also contributes to human myopia by mediating interactions between genetic and environmental factors." (PMID 39796188, 2025). "In this study, salidroside was found to suppress the infiltration of proinflammatory macrophages, their expression of hypoxia-related Car1 and HIF-1α, and further the progression of myopia." (PMID 41330940, 2025). "This hypoxia influences scleral ECM remodeling and myopia development by activating the HIF-1α signaling pathway." (PMID 40933557, 2025). "Salidroside, a common anti-hypoxic drug, has been reported to suppress the upregulation of HIF-1α and inhibit the progression of experimental myopia in guinea pigs by periocular injection." (PMID 41330940, 2025). "Recent evidence suggests that, in fact, anti-hypoxia drugs reducing Hif-1α levels can slow axial elongation, which points towards a possible relationship between myopia, hypoxia and Hif-1α." (PMID 37275358, 2023). "Among them, HIF-1α has been studied more frequently and is also the main relevant factor affecting myopia." (PMID 36961150, 2023). "This view is supported by in vivo studies that hypoxia-inducible factor-1α (HIF-1α) was upregulated in the myopic sclera, which promoted myopia through fibroblast-to-myofibroblast transdifferentiation." (PMID 31839753, 2019). "Bridging molecular insights (e.g., hypoxia-HIF-1α-MMP-2 axis) with innovations like gene editing is essential to curb myopia progression, necessitating prioritized research on multiple pathways interaction and translational trials to advance precision ocular therapies." (PMID 40933557, 2025). "Additionally, HIF-1α impacts angiogenesis and cellular metabolism, further exacerbating myopia development." (PMID 40933557, 2025).